CD44 (CD44 molecule (IN blood group))
Diseases named in the same sentence as CD44 in open-access papers (continued):
Sharing a sentence is not in itself a finding about the gene and the disease.
tumor (continued). "Although these regimens demonstrate attractive anti-tumor efficacy, there are no anti-CD44 therapeutics available in the clinic for OC patients, potentially owing to the substantial side effects on normal stem cell which expresses high level of CD44." (PMID 31277278, 2019). "CSCs have been identified and isolated, based on the expression of specific molecules, such as CD24, CD34, CD44, CD133, and aldehyde dehydrogenase (ALDH), and are able to regenerate tumor mass from a small number of cells when implanted into immunodeficient mice." (PMID 31013960, 2019). "A tumor-initiating CSC population in RCC has been defined by the expression of CD105, CD44, and CD73 cell surface markers, and TG2 was found to be necessary for maintenance of the CD105+/CD44+/CD73+ phenotype in metastatic Caki-1 RCC cell population." (PMID 30736384, 2019). "PACSL cells expressing RON, CD44, and ESA are known to be tumor-initiating stem-like cells." (PMID 31519211, 2019). "Together, these data suggest that neither CD44 expression by MDA-MB-468 tumor cells, nor its interaction with HA, is necessary for the enhanced tumor growth in the presence of the engineered 3T3HAS3 fibroblast cells." (PMID 31762938, 2019). "Furthermore, treatment with DSF/Cu or BKM120 induced higher levels of apoptosis in ALDH+ or CD44+/CD24− populations, respectively, than in bulk tumor cells." (PMID 30659204, 2019). "Interestingly, the abundance of Ep‐CAM+/CD44+ cells in distal margin and Ep‐CAM+/CD133+ cells in tumour tissues was intriguing." (PMID 30950180, 2019). "ObR and CD44 increased in tumor line cells, and vimentin increased in non-tumor cells, after incubation with hRAT-CMs vs. hRAN-CMs and control-CMs." (PMID 31534630, 2019). "In addition to that, Kaplan‐Meier plot showed significantly lower DFS for CD133 enriched group in distal margin compared to control group as well as CD44‐ and CD133 enriched group of tumour." (PMID 30950180, 2019). "Although we digested the MDA-MB-231 tumor spheres into single cells and injected these into the zebrafish, these did not migrate until the sixth day, suggesting that CD44+CD24- is not a suitable marker for MDA-MB-231 stem cells." (PMID 31612865, 2019). "Although the prognostic value of CD44 is controversial, a meta-analysis comprising 14 studies with more than 2200 patients showed that CD44 expression was directly correlated with the pTNM stage but not with the tumor grade or AFP serum level." (PMID 31781608, 2019). "Furthermore, asporin is also positively or negatively correlated with tumor proliferation, migration, invasion, and patient prognosis through its regulation of different signaling pathways, including the TGF-β, EGFR, and CD44 pathways." (PMID 31608236, 2019). "For example, injection of a hundred CD44+CD117+ cells isolated from OC patient tumors was capable of propagating the original tumor; however, CD44−CD117− cells were nontumorigenic." (PMID 31277278, 2019). "For example, tumor cells with high expression of CD44 (but not cells with low CD44 expression) have been shown to induce the formation of tumors in animals with a small numbers of tumor cell injection." (PMID 31293964, 2019). "Enriched expression of CD44 and CD133 in tumour and distal margin could suggest the presence of disseminated cells from the tumour (residual cells) or may be due to the molecular alteration caused by treatment given." (PMID 30950180, 2019). "Recently, asporin expression was also shown to be dysregulated in tumor tissues and positively or negatively correlated with tumor proliferation, migration, invasion, and patient prognosis by regulating different signaling pathways, including the TGF-β, EGFR, and CD44 pathway." (PMID 31608236, 2019).
tumor (continued). "This study demonstrated that M (mesenchymal, CD44+/CD24−) and E (epithelial, ALDH+) CSCs were distinct populations with different patterns in tumor distribution, gene expression, proliferation, and quiescence, suggesting different functionalities of these two CSC subpopulations." (PMID 31394796, 2019). "In a follow-up experiment, we found that upregulated PAX6 expression elevated the expression of EMT marker genes (N-cadherin, vimentin, FSP-1), stem cell biomarkers (CD44, CD133, ALCAM), and the proliferation marker Ki67, yet it inhibited E-cadherin in tumor tissues as assessed by IHC." (PMID 31024010, 2019). "However, the tumor sphere numbers and CD133+ cell percentages were decreased when exosomes were inhibited in G‐MDSCs and M‐MDSCs, but the CD44+ cell percentage was decreased only when exosomes were inhibited in G‐MDSCs." (PMID 31559140, 2019). "Investigation with different CD44 expressing cell lines (MCF-7, 4T1) and 4T1 tumor-bearing mice suggested that deprotonation of PHIS around pH 6.5 (a pH value close to that of the tumor microenvironment) switched the nature of NPs from hydrophobic to hydrophilic." (PMID 31635367, 2019). "Despite no detectable effect from knocking down/out CD44 expression in this experimental system, enzymatic degradation of HA consistently inhibited the growth of the engineered xenograft tumor model with HA-accumulating stroma." (PMID 31762938, 2019). "Detection of CSCs with ALDH1 and CD44 was not straightforward because tumor-infiltrating macrophages were often a prominent component of the tumor and they also expressed CD44 and ALDH1." (PMID 30999901, 2019). "Recent data has shown that CD44 and its principal ligand hyaluronan (HA) are carried by extracellular vesicles (EV) derived from stem and tumor cells, but the role of CD44 in EV shedding has not been studied so far." (PMID 30909497, 2019). "Indeed, the markers CD44, CD95, and Ly-6C were expressed at low levels in NFs from tumor-bearing mice, suggesting a mainly activation- and proliferation-associated role and regulation." (PMID 31428583, 2019). "CD44, a widely expressed membrane adhesion molecule, is reported to be responsible for various biological and functional processes such as cell adhesion, growth, epithelial-mesenchymal transition (EMT) and tumor progression." (PMID 30451890, 2018). "The selective binding of HA-CH-NP/siRNA to CD44-positive tumor endothelial cells increased by 2.1-fold compared with that of the CD44 nontargeted CH-NP/siRNA." (PMID 29890852, 2018). "At cut off >5% of tumour cells with positive staining, 62%, 59%, 65% and 45% of the cases were EGFR, HER-2, HER-3 and HER-4 positive, and 3%, 22% and 48.3% of the cases were positive for EGFRvIII, c-MET, and CD44 respectively." (PMID 29731973, 2018). "On the other hand, applying anti-miR34a or miR-34a antagomir to CD44-negative cells promoted tumor growth." (PMID 29747682, 2018). "Recently, some studies indicated that CRC tumor budding cells had high expression of markers of cancer stem cells, such as CD44, CD133 and ABCG5, and suggested that some tumor budding cells in CRC might contain subgroups of cancer stem cells." (PMID 30046385, 2018). "IF analysis confirmed the presence of the CD44 protein in all four tumor types with minimal staining in normal brain tissue." (PMID 29352201, 2018). "Calcitriol treatment can also deplete the ovarian CSC population characterized by ALDH+ and CD44+CD117+; decrease their capacity to form sphere under the CSC culture condition, and reduce the frequency of tumor-initiating cells, as evaluated by in vivo limiting dilution analysis." (PMID 29581858, 2018). "CD44 expression is no doubt weaker in neoplastic tissue than in healthy tissue and weaker in poorly differentiated neoplasia than in well-differentiated neoplasia, resembling the behavior of other adhesions molecules such as E-cadherin." (PMID 29682524, 2018).
tumor (continued). "The reason why some Hi-I type of GSCs expressing high levels of CD44 also show strong tumor proliferation is not clear." (PMID 30210550, 2018). "Compared to the original tumor, R2J cells in culture (2D and spheres) lost the GFAP and CD56 expressions (only 2D) whereas Ki67, vimentin and nestin expressions were conserved as well as mesenchymal shift markers, such as CD44." (PMID 30583471, 2018). "Likewise, primary TNBC patients’ tumor samples (CRDCA, SEM‐1, and ARI‐1) also showed increased expression of E‐cadherin, active β‐catenin, and ALDH but decreased expression of YAP and CD44." (PMID 29316250, 2018). "In addition, this combination increased the central memory (CD62+ CD44+) in the TME, enhancing the durability of anti-tumor immune response." (PMID 30400835, 2018). "In fact, according to our in vivo results, the GFAP/CD133+CD90+/CD44+ cells maybe the cell population responsible for EPN dissemination, leading to reduced patient survival due to the inherent chemoresistance of this tumor." (PMID 29774098, 2018). "Since the tumour and derived cell line were enriched with EMT traits, and both, polygonal and spindle cells in the tumour expressed CD44, it appears reasonable to consider that both components may have arisen from EMT." (PMID 30185896, 2018). "Following long-term HER2 siRNA treatment, the population distribution remains largely the same, without any detectable emergence of a CD24-/CD44+ population, suggesting no enrichment of tumor initiating cells." (PMID 29879129, 2018). "Among these 10 CD antigens, we found that the CD44-positive fraction in human CRC cell lines were more resistant to tumor specific CTL-mediated killing compared to the CD44-negative fraction." (PMID 30400822, 2018). "CD44v8-10 but not CD44s expression rescued the tumor-initiation potential of gastric cells in which total CD44 was depleted." (PMID 29747682, 2018). "Moreover, Notch signaling induced EMT, increased CD44+ PCSC, aggressive tumor behavior and resistance to conventional chemotherapy." (PMID 30004402, 2018). "In addition to CD44, VEGF was the most highly expressed molecule, not only in the tumor periphery but also in the core." (PMID 30210550, 2018). "The capability of the breast metastatic CD44−CD24+ cells isolated from bone to generate new heterogeneous tumors with a high percentage of CD44+CD24− CSCs is consistent with a phenotypic plasticity of these cells, that allow metastatic cells to regain a tumor-initiating capacity." (PMID 29461491, 2018). "Therefore, the endothelial cells in the A2780 tumor tissue expressed CD44, thus providing an attractive tumor model for targeting both PLXDC1 and CD44 in tumor endothelial cells." (PMID 29890852, 2018). "In addition, the stemness marker proteins CD44, Oct-4, Nanog, as well as Bcl-2 and MMP-9 expression levels of ALDH+ cells were upregulated compared with the original tumor cells, indicating that they have certain stem cell characteristics." (PMID 29914196, 2018). "Moreover, we tested the therapeutic efficacy of the HeyA8 tumor model, which is a PLXDC1- and CD44-positive cell line." (PMID 29890852, 2018). "Emergence of CD44+/CD24+ MCF7 cells, also positive for another stem cell marker CD49f, could result from increased stemcell-like populations in the hypoxic tumor microenvironment in vivo." (PMID 29510720, 2018). "Moreover, CD44 and CD133 are hepatic CSCs markers 20, 21, and CSCs can transdifferentiate into endothelial cells to promote tumor angiogenesis." (PMID 29683262, 2018). "Comparing tumour infiltrating ILC populations with circulating ILC, showed that ILC populations have an activated phenotype in tumour tissue with higher expression of MHC-II, KLRG1, CD69 and CD44." (PMID 29587679, 2018). "Similarly, si-hVDAC1 treatment of A549-derived tumours greatly decreased the expression of ABCG2, SOX2, CD44, CD144, CD133, KLF4, Oct3/4, EPCAM and Nanog, also as evaluated by IHC, immunoblotting or q-RT-PCR." (PMID 30544833, 2018).
tumor (continued). "Although the EGFP+ tumor cells displayed robust mTOR phosphorylation, the mTOR inhibitor, rapamycin, did not strongly affect the CSC-associated CD24 and CD44 markers (data not shown)." (PMID 29510720, 2018). "Because OPN plays a crucial role in tumor progression and metastasis through binding to CD4444,45, we compared the levels of OPN and the capacity for HCV replication in EpCAM+/CD44+ CSCs and EpCAM−/CD44− cells." (PMID 30177680, 2018). "Consequently, the CD44/MMP9 complex cannot form, thus blocking tumor cell metastasis and arteriogenesis in the MCF-7 cell line." (PMID 29872510, 2018). "On the other hand, tubular epithelial cells were negative for CD44, while numerous CD44-positive polygonal and spindle tumour cells were observed." (PMID 30185896, 2018). "We next examined the in vivo selective delivery of HA-CH-NP/Cy5 siRNA in A2780 tumor-bearing mice following i.v. injection, because the tumor endothelial cells were CD44-positive but the A2780 cells were CD44-negative." (PMID 29890852, 2018). "Evidence points towards CD44 for the identification of CSCs in HNSCC as in other tumor entities." (PMID 29693014, 2018). "Furthermore paracrine signaling of non-endogenous overexpressed RANKL in human breast cell lines increases the CD44+CD24− BCSC pool, promoting tumor initiation and metastasis." (PMID 29600163, 2018). "Interestingly, in GC, ALDH+ cells represent 1.6% to 15.4% of the tumor CSC and contain higher frequency of tumorigenic CSCs than CD44+ cells." (PMID 30380687, 2018). "In this process, CD44, highly expressed during GMT, plays an important role in the implantation of tumor cells, allowing the initiation of a metastatic cascade related to the modulation of several cellular characteristics, including adhesion, motility, and matrix degradation." (PMID 30583471, 2018). "CD24+CD44+ fraction when administered at various doses (2 × 104 down to 100 cells/mouse) did not allow the tumor growth." (PMID 28622715, 2017). "However, a previous study showed that high levels of HA are present in the margins of solid tumor tissue, and the HA receptors CD44 and RHAMM are highly expressed on the surface of the tumor cells." (PMID 28155337, 2017). "Numb− MECs derived from PDXs treated in vivo with Nutlin‐3, either alone or in combination with paclitaxel, displayed significant reduction in SFE and tumor formation (middle and right), accompanied by decreased ALDH activity or reduced number of CD44+/CD24− cells." (PMID 28298340, 2017). "However, NAMPT-underexpressing cells showed clear reductions in the CD133+ and CD44+ pools, confirming that NAMPT is a factor that facilitates tumor cell de- differentiation to a pluripotent-like state." (PMID 29245920, 2017). "Moreover, we evaluated the expression of CD44 and CD24 in those murine tumour samples to assess the co-expression of EMT markers and surrogate markers associated with a CSC phenotype." (PMID 28388884, 2017). "In the present study, we addressed the role of autophagy in the maintenance of the CD44+CD117+ cell pool; we found that autophagy is hyper-activated in ovarian CSC and that this aberrant activation may contribute to chemoresistance and tumor relapse." (PMID 28726781, 2017). "Despite genomic similarity between the bulk tumor and the EPCAM+CD44+CD49f+ cells, principal component analysis demonstrated heterogeneity among bulk tumor regions, lymph nodes, as well as the derived EPCAM+CD44+CD49f+ subpopulations." (PMID 28487492, 2017). "Afterwards, tumours were stained against Six1, CD24 and CD44." (PMID 28388884, 2017). "The primary tumour was CD44-negative on tumour cells, but stained positive in clusters of CD45+ immune cells." (PMID 28417956, 2017). "CD44+ tumors, exemplified by MU028, exhibited an invasive growth pattern with multifocal infiltration of tumor cells into the normal brain parenchyma, appearing as discrete non-encapsulated clusters and swirls of densely packed tumor cell surrounded by normal brain cells." (PMID 28241049, 2017).
tumor (continued). "CD44 expression in IL-15/trastuzumab treated HTM was increased in spleen, tumor, and liver." (PMID 27835865, 2017). "Importantly, miR-141 oligo transfection inhibited both tumour incidence and weight in vivo in CD44+ DU145 cells and PPC-1 tumour regeneration." (PMID 28112170, 2017). "Within the tumor microenvironment of mGITRL-FP-treated CEA.Tg mice, a significant reduction in the percentage of Ki67+/CD44+ CD4+FoxP3- T cells was found, while the frequencies of both CD4+FoxP3+ and Ki67+/CD44+ CD8+ T cells trended downward." (PMID 29088720, 2017). "After a 4-hour perfusion of antibody solution of both EpCAM and CD44, the antibodies could be seen throughout the FNAB tumor sample." (PMID 28085924, 2017). "In fact, a subpopulation of cancer cells enriched as tumor-initiating cells with the antigenic phenotype CD44+/CD24- has been increasingly found in metastatic breast cancer, in comparison to the majority of carcinoma cells, which are CD44-/CD24+ phenotype." (PMID 28609459, 2017). "This might be because that SK-BR-3 had lower CD44/CD24 ratio compared to MDA-MB-231, which might also contribute to slower tumor migration and metastasis." (PMID 29062075, 2017). "Finally, we found that the CD44/CD24 ratio and ALDH1+ were stable during the tumor growth and metastasis, from the primary tumor to the distant metastases." (PMID 29062075, 2017). "As expected, NB5t primary cells showed increased expression of mesenchymal genes (NT5E, ENG, ACTA2, MME, CD44, VIM or ALPL), while NB5t tumor sample expressed mostly neuronal genes (TH, ENO2, NCAM1, DDC or CHGB) reflecting the neuroblastic phenotype of stage 4/M NB tumors." (PMID 29163787, 2017). "P450-derived eicosanoids overexpression can promote human cancer metastasis by increasing CD44 expression and our results demonstrated a significant decrease in cancer stem cell markers, such as CD44 and N-cadherin in lungs of HPßCD-HET0016 treated group and in the primary tumor." (PMID 28609459, 2017). "While CD44+/CD24− cells may be sensitive to some inhibitors, they often drive tumor resistance to traditional therapies." (PMID 28445439, 2017). "However, Gβγ blockage decreases the frequency of CD133+/CD44+ populations in PC3 cells in vitro and in tumor xenografts, supporting the idea that Gβγ blockade does affect CSCs." (PMID 28415604, 2017). "Enrichment for gene sets related to lipid metabolism and the immune system in the EPCAM+CD44+CD49f+ cells compared to the bulk tumor population, which included tumor-infiltrating and stromal cells, may represent pathways unique to EPCAM+CD44+CD49f+ cells." (PMID 28487492, 2017). "It is remarkable that LACHA-DOX achieves effective inhibition of CD44 positive LP-1 and AML-2 tumors without causing side effects, leading to significantly improved survival rate for both LP-1 and AML-2 tumor-bearing mice." (PMID 28958164, 2017). "To verify this hypothesis, we analyzed chromosomal aberrations, transcriptome changes, and the presence of CD44+CD24- CSCs in different morphological structures: tubular, solid, alveolar, and trabecular structures, as well as discrete groups of tumor cells." (PMID 28977854, 2017). "In addition, we also observed that CD44+/CD24− cells from tumor and tumor-derived cell lines, as well as cells that have been exposed to TGF-β, had an increased clonal genetic diversity." (PMID 28092266, 2017). "Isolated from solid biopsies and tumor cell lines, cancer stem cells are currently identified by surface antigen expression using a number of putative stem cell markers including CD15, CD24, CD44, and CD133." (PMID 28399903, 2017). "Moreover, there was a significant correlation between the expression level of CD44 and PDE3A in the PDAC cell lines Panc-1, BxPC-3 and MIA PaCa-2, as well as the tumor tissues derived from PDAC patients." (PMID 28507327, 2017).